HADHB (hydroxyacyl-CoA dehydrogenase trifunctional multienzyme complex subunit beta)
Diseases named in the same sentence as HADHB in open-access papers:
HADHB is named in the same sentence as 58 diseases in open-access papers, as found by Europe PMC text mining. Sharing a sentence is not in itself a finding about the gene and the disease. The quoted sentences say what the papers report.
mitochondrial trifunctional protein deficiency (7 papers, 2018 to 2025). "HADHA and HADHB cause mitochondrial trifunctional protein deficiency (MTPD), leading to peroneal muscular atrophy." (PMID 34107874, 2021). "Mitochondrial trifunctional protein deficiency (MTPD) is a rare autosomal recessive disorder caused by pathogenic variants of HADHA or HADHB." (PMID 34712195, 2021). "Mutations in the HADHB gene have been associated with mitochondrial trifunctional protein deficiency." (PMID 29507648, 2018). "Mitochondrial trifunctional protein deficiency (MTPD) is diagnosed when mutations in HADHA or HADHB (a beta subunit of mitochondrial trifunctional protein) genes lead to a deficiency of all enzyme activities in the MTP complex." (PMID 37834305, 2023). "Family F4367 was clinically diagnosed with HADHB-related non-syndromic peripheral neuropathy, which is a distinct allelic disorder from the OMIM-listed HADHB-related trifunctional protein deficiency." (PMID 37644014, 2023).
cardiomyopathy (6 papers, 2013 to 2022). A disease of the heart muscle or myocardium proper. "Recessive HADHB mutation results in the dysfunction of the beta-oxidation of fatty acids, leading to MTP deficiency, characterized in a severe heterogeneous syndrome, such as cardiomyopathy, recurrent Leigh-like encephalopathy, hepatopathy, and neonatal or unexpected infant death." (PMID 35235001, 2022). "However, they did not have any other previously reported symptoms of HADHB patients, such as a rhabdomyolysis, cardiomyopathy, hypoketotic hypoglycemia, metabolic encephalopathy, liver dysfunction, nor pigmentary retinopathy." (PMID 24314034, 2013).
colorectal cancer (5 papers, 2018 to 2025). A primary or metastatic malignant neoplasm that affects the colon or rectum. "HADHB was downregulated in colorectal cancer (CRC), and further functional analysis indicated that it reduced cancer cell migration and invasiveness." (PMID 31777589, 2019). "The differences in methylation, hydroxymethylation, and transcriptional expression of HADHB between cancerous and normal tissues were confirmed in additional colorectal cancer patients." (PMID 29507648, 2018). "The methylation of five genes (AHCYL2, IL11RA, SEMA6D, BIRC3, and HADHB) was associated with tumors, and four genes (IL11RA, CHL1, SEMA6D, and BIRC3) were associated with colorectal cancer." (PMID 29507648, 2018). "To evaluate the potential contribution of the HADHB gene to tumorigenesis, we further performed gene knockdown and overexpression experiments in colorectal cancer cell lines." (PMID 29507648, 2018). "Additionally, in colorectal cancer and stomach adenocarcinoma, HADHB has been proposed as a tumor suppressor, its expression being significantly lower in tumors compared to normal tissue." (PMID 37601653, 2023). "Furthermore, hypermethylation of the hydroxyacyl-CoA dehydrogenase trifunctional multi-enzyme complex subunit beta gene (HADHB) was persistently found to be correlated with its transcriptional downregulation in colorectal cancer (CRC)." (PMID 29507648, 2018). "Furthermore, hypermethylation of the HADHB gene was persistently found to be correlated with downregulation of its transcription in colorectal cancer (CRC)." (PMID 29507648, 2018). "AGPAT4, ENTPD1, HADHB, CA12, CA9 was reported in colorectal cancer." (PMID 33815132, 2021).
neuropathy (5 papers, 2021 to 2025). A disorder affecting the nervous system that manifests with pain, tingling, numbness, and/or muscle weakness. "This case also highlights the need for HADHA and HADHB to be included in neuropathy gene panels as MTPD may present as CMT." (PMID 40790338, 2025).
LCHAD deficiency (3 papers, 2018 to 2024). "Moreover, the impact of HADHA and HADHB mutations found in patients with TFP/LCHAD deficiency on CL content or structure has only been cursorily investigated in isolated LCHAD deficiency due to the HADHA c.1528G>C (p.E510Q) mutation." (PMID 39088276, 2024). "Mutations in HADHA are responsible for LCHAD deficiency (LCHADD), whereas variants in HADHA and HADHB cause MTP deficiency (MTPD)." (PMID 35806149, 2022).
malignant lymphoma (3 papers, 2022 to 2025). "HADHA, which forms a heterodimer together with HADHB, is also widely up-regulated in malignant lymphomas, and down-regulation of HADHA can cause G0/G1 cell cycle arrest." (PMID 36106108, 2022). "As an enzyme involved in FAO, HADHB is commonly overexpressed in malignant lymphomas and is a poor prognosis predictor in DLBCL, and high expression of HADHB promotes the proliferation and growth of malignant lymphomas." (PMID 36106108, 2022). "HADHA in lung carcinomas and both HADHA and HADHB in malignant lymphoma." (PMID 37601653, 2023). "Moreover, both HADHA and HADHB enzymes have been found overexpressed in malignant lymphoma progression, relying on fatty acid metabolism and notably FAO as a key metabolic pathway for tumor progression and survival." (PMID 37601653, 2023).
and sensory neuropathy (2 papers, 2013 to 2021). "The present study supports the notion that HADHA- or HADHB-related motor and sensory neuropathy should be considered as a CMT subtype." (PMID 34712195, 2021). "Thus our findings suggest that HADHB gene can be also filed as a causative of CMT, which expands the clinical spectrum of both HADHB related disease and hereditary motor and sensory neuropathy." (PMID 24314034, 2013).
hepatocellular carcinoma (2 papers, 2018 to 2025). A malignant tumor that arises from hepatocytes. "Hypermethylation in the HADHB gene was found in hepatocellular carcinoma." (PMID 29507648, 2018).
ischemia (2 papers, 2019). A hypoperfusion of the BLOOD through an organ or tissue caused by a PATHOLOGIC CONSTRICTION or obstruction of its BLOOD VESSELS, or an absence of BLOOD CIRCULATION. "Expression of both CIRBP and HADHB was upregulated after hindlimb ischemia in mice." (PMID 30665182, 2019).
rhabdomyolysis (2 papers, 2013 to 2025). Necrosis or disintegration of skeletal muscle often followed by myoglobinuria. "Genetic data suggest an increased susceptibility to rhabdomyolysis in individuals of Japanese descent, due to specific mutations in genes involved in muscle metabolism, such as HADHA, HADHB, CACNA1S, and HLA-DRB1* 04:06." (PMID 40709115, 2025).
acute myeloid leukaemia (1 paper, 2022). "In recent years, extensive reports have demonstrated the tumour suppressing roles of HADHB in various cancers, such as colorectal cancer (CRC), oral squamous cell carcinoma (OSCC), and acute myeloid leukaemia (AML)." (PMID 36518312, 2022).
Anxiety (1 paper, 2025). Intense feelings of nervousness, tension, or panic often arise in response to interpersonal stresses. "For HADHB rs6745226, the A allele is also associated with increased risks of anxiety and depression." (PMID 40002435, 2025).
clear cell renal cell carcinoma (1 paper, 2022). "Previously, HADHB expression was found to be positively correlated with the OS of clear cell renal cell carcinoma (ccRCC) patients." (PMID 36518312, 2022).
colorectal tumors (1 paper, 2018). "To confirm that the expression level of the HADHB gene was associated with its methylation and hydroxymethylation levels in a larger population, we collected 15 additional pairs of samples from colorectal tumors and their adjacent normal tissues." (PMID 29507648, 2018).
epilepsy (1 paper, 2022). A brain disorder characterized by episodes of abnormally increased neuronal discharge resulting in transient episodes of sensory or motor neurological dysfunction, or psychic dysfunction. "Epilepsy was described previously in a Korean patient with two novel HADHB mutations which presented on day 5 with lactic acidosis and seizures." (PMID 35782614, 2022).
familial hypertrophic cardiomyopathy (1 paper, 2020). Hypertrophic cardiomyopathy caused by mutations in the genes encoding components of the sarcomere, in the absence of predisposing conditions. "Human genome-wide association studies (GWAS) have indicated that mutations in HADHA and HADHB are associated with familial hypertrophic cardiomyopathy, and mutations in CPT1, ACADM, and ACAA2 genes are associated with impaired mitochondrial fatty acid β-oxidation." (PMID 32804947, 2020).
Hypoglycemia (1 paper, 2025). A decreased concentration of glucose in the blood. "Biallelic variants in HADHB adequately explained some features including hypoglycemia, retinopathy, hepatomegaly, and hypoparathyroidism." (PMID 39723123, 2025).
metabolic myopathy (1 paper, 2021). A group of rare inherited disorders characterized by a deficiency of enzymes that are involved in metabolic pathways that affect muscles. "Thus, we report a new subtype of CMT with metabolic myopathy due to MTPD deficiency caused by mutations of HADHB gene, suggesting that all CMT patients without definite pathogenic mutations should be screened for mutation in HADHA and HADHB genes." (PMID 34712195, 2021). "The HADHA and HADHB gene should be added into the screening panel for CMT and metabolic myopathy." (PMID 34712195, 2021).
Wilms’ tumour (1 paper, 2022). "HADHB is a fatty acid beta-oxidation enzyme that was found to be downregulated in multiple cancers, such as OSCC, AML, and Wilms’ tumour." (PMID 36518312, 2022).
cancer (6 papers, 2018 to 2025). A tumor composed of atypical neoplastic, often pleomorphic cells that invade other tissues. "HADHB, important in mitochondrial fatty acid β-oxidation, is linked to tumor metabolism changes in various cancers." (PMID 40875107, 2025). "IHC analysis revealed a significantly elevated protein expression of HADHB in the cancer tissue specimens of the 5FU-insensitive group compared to the 5FU-sensitive group." (PMID 40875107, 2025). "To further validate these findings, we performed functional analyses and found that the overexpression of HADHB clearly reduced cancer cell migration and invasiveness." (PMID 29507648, 2018). "HADHB is known as a tumour suppressor gene in various cancers." (PMID 36518312, 2022). "HADHB was found to have a low expression in various cancers, including STAD." (PMID 36518312, 2022). "Therefore, our findings implicated HADHB as a potential biomarker for the diagnosis and treatment of CRC, especially for alleviating and controlling cancer progression." (PMID 29507648, 2018). "Tumor functional analysis indicated that HADHB reduced cancer cell migration and invasiveness." (PMID 29507648, 2018). "We further observed that combined HADHB knockdown and 5-FU treatment significantly increased the efficiency of cell cycle arrest in CRC cells, suggesting that reduced ROS levels might help inhibit cancer cell proliferation." (PMID 40875107, 2025).
tumor (6 papers, 2018 to 2025). "HADHB upregulation also suppressed various tumour cell phenotypes, such as cell viability, proliferation, and migration." (PMID 36518312, 2022). "HADHB upregulation impeded tumour growth and cell proliferation, and enhanced apoptosis in nude mice." (PMID 36518312, 2022). "In this study, we analysed the expression of HADHB in 24 tumours using UALCAN and data obtained from TCGA database." (PMID 36518312, 2022). "Further, the viability, proliferation, colony formation, cell cycle determination, migration, and wound healing capacity were assessed, and the effects of HADHB on tumour growth, cell apoptosis, and proliferation in nude mice were determined." (PMID 36518312, 2022). "The upregulation of KLF4 distinctly relieved the HADHB knockdown-induced tumour promoting effects on cell viability (P < 0.05 or P < 0.01), invasion, and migration (both P < 0.05)." (PMID 36518312, 2022). "The reduced expression of HADHB triggered a series of tumour promoting effects by regulating the Hippo-YAP signalling pathway in STAD." (PMID 36518312, 2022). "The upregulation of KLF4 also notably abolished the HADHB knockdown-induced tumour promoting effects on cell viability, migration, and invasion." (PMID 36518312, 2022). "Collectively, these results indicate that HADHB upregulation led to tumour suppressive effects in STAD cells by regulating the Hippo-YAP signalling pathway." (PMID 36518312, 2022). "We found the expression levels of HADHB in tumor tissues (0.18 ± 0.15) were significantly lower than those in normal tissues (0.32 ± 0.24) (P = 0.025)." (PMID 29507648, 2018). "Collectively, these findings imply that KLF4 might play a tumour suppressing role in STAD by interacting with the HADHB promoter at the 361-371 site to regulate its expression." (PMID 36518312, 2022). "Collectively, these findings indicate that KLF4 might play a tumour suppressing role in STAD by regulating HADHB expression and modulating its downstream gene expression, such as proliferation- or metastasis-associated genes." (PMID 36518312, 2022). "KLF4 upregulation abolished the HADHB knockdown-induced tumour promoting effects in AGS cells." (PMID 36518312, 2022). "HADHB might function as a tumour suppressor gene in STAD by regulation the Hippo-YAP pathway." (PMID 36518312, 2022). "Taken together, these functional experiments support the hypothesis that HADHB is a potential tumor suppressor gene, which can reduce tumor cell invasiveness and migration, suggesting that silencing HADHB may contribute to colorectal oncogenesis and progression." (PMID 29507648, 2018). "We confirmed that HADHB could be a novel tumor suppressor gene." (PMID 29507648, 2018). "The functional studies indicated that HADHB might act as a tumor suppressor gene." (PMID 29507648, 2018). "For example, we identified five lysine acetylation sites in HADHA, four lysine acetylation sites in HADHB, and three lysine acetylation sites in both ACADVL and PCCA, all of which showed lower acetylation levels in tumor tissues." (PMID 33093847, 2020).
peripheral neuropathy (5 papers, 2013 to 2024). A disorder affecting the peripheral nervous system. "As described for Patient 3, peripheral neuropathy may be the main symptom in patients with HADHB mutations, or at least in certain stages of the disease course." (PMID 35235001, 2022). "Therefore, further analyses are needed to elucidate the pathophysiological mechanism of HADHB mutation-mediated peripheral neuropathy." (PMID 24314034, 2013). "This lncRNA genetically interacted with other genes associated with peripheral neuropathy, such as cytochrome C oxydase assembly factor 7 (COA7), hydroxyacyl-CoA dehydrogenase/3-ketoacyl-CoA thiolase/enoyl-CoA hydratase beta (HADHB), and pyruvate dehydrogenase beta (PDHB), in Drosophila." (PMID 33419039, 2021). "Recently, it was suggested that peripheral neuropathy related to HADHB mutations may be manifested as axonal CMT without other MTP deficiency symptoms." (PMID 34712195, 2021).
hereditary peripheral neuropathy (1 paper, 2021). An instance of peripheral neuropathy that is caused by an inherited genomic modification in an individual. "If the HADHB gene had been included in the screening panel for hereditary peripheral neuropathy, our patient would have received the correct genetic diagnosis 14 years earlier, resulting in proper treatment with better outcomes and improved quality of life." (PMID 34712195, 2021).
metabolic disorder (1 paper, 2017). "Mutations in MTP genes (HADHA and HADHB), both located on chromosome 2p23, cause MTP deficiency, a rare autosomal recessive metabolic disorder characterized by decreased activity of MTP." (PMID 29095929, 2017).
HADHB also shares sentences with these, for which no sentence is quoted: hepatopathy (3 papers); hyperlipidaemia (2); infection (2); Obesity (2); amyotrophic lateral sclerosis (1); Atrophy (1); axonal sensory neuropathy (1); cerebellar ataxia (1); Charcot-Marie-Tooth disease (1); cholestasis (1); COVID-19 (1); Creutzfeldt-Jakob disease (1); deafness (1); depression (1); diffuse large B-cell lymphoma (1); hereditary sensory neuropathy type 1E (1); hyperglycaemia (1); hypoparathyroidism (1); Insulin resistance (1); ischemic heart disease (1); lactic acidosis (1); lung carcinoma (1); myopathy (1); narcolepsy (1); Neonatal sepsis (1); pancreatic cancer (1); Parkinson disease (1); peroxisomal biogenesis disorder (1); Pigmentary retinopathy (1); proteinopathies (1).
A further 4 diseases each share a sentence with HADHB in 1 paper.